DNAJB3 (DnaJ heat shock protein family (Hsp40) member B3 )
Synonyms: HCG3; DNAJB3P
Gene: Long non-coding RNA gene on chromosome 2 (233,742,750 to 233,744,015, reverse strand). Ensembl gene ENSG00000293135.
Diseases named in the same sentence as DNAJB3 in open-access papers:
DNAJB3 is named in the same sentence as 8 diseases in open-access papers, as found by Europe PMC text mining. Sharing a sentence is not in itself a finding about the gene and the disease. The quoted sentences say what the papers report.
Obesity (8 papers, 2013 to 2023). Accumulation of substantial excess body fat. "The decrease in the expression of DNAJB3 in obese and T2D subjects and the restoration of its normal expression by physical exercise are suggestive of a protective role of DNAJB3 against obesity associated metabolic stress." (PMID 37594932, 2023). "All these observations suggest a protective role of DNAJB3 against obesity associated metabolic stress." (PMID 30886231, 2019). "Although we did not demonstrate the causal relationship between reduced expression of DNAJB3 and obesity, we demonstrated that DNAJB3 is part of a complex that contains key proteins involved in obesity, insulin resistance and T2D such as HSP-72, JNK and IKKβ." (PMID 23894433, 2013). "This is the first report that DNAJB3 deficiency could play a potential role in the development of obesity and associated glucose intolerance and inflammation." (PMID 37895206, 2023). "The chronic conditions associated with obesity such as low grade metabolic inflammation, hyperlipidemia, and enhanced oxidative and ER stress responses promoted us to explore the possible mechanisms involved in modulating the expression of DNAJB3." (PMID 23894433, 2013). "In order to gain new insights into the role that DNAJB3 may play in the context of obesity and the functional consequences associated with its reduction in obese subjects, we sought to investigate the partners of interaction that associate with it using coimmunoprecipiation assays." (PMID 23894433, 2013). "Restoring the normal expression of DNAJB3 attenuated metabolic stress and improved insulin signaling both in vivo and in vitro, suggesting a protective role of DNAJB3 against obesity and T2D." (PMID 37895206, 2023). "We previously showed, for the first time, impaired expression of DNAJB3 mRNA and protein in subjects with obesity, which was concomitant with increased metabolic stress." (PMID 37895206, 2023). "We previously reported impaired expression of DNAJB3 mRNA and protein in the WAT of subjects with obesity, that was associated with increased inflammatory response and altered metabolic profile." (PMID 37895206, 2023). "For example, we have previously showed that exercise is an important regulator of DNAJB3 protein a member of the HSP40 protein family that has been shown to be downregulated by obesity and upregulated after physical exercise." (PMID 28264047, 2017). "Identification of the function of DNAJB3 and its importance in obesity needs to be addressed in the future." (PMID 26147428, 2015). "The downregulation of DNAJB3 in clinically relevant tissue organ can be added to the list of component of the HSR that are attenuated by obesity in human subjects." (PMID 23894433, 2013). "Taken together, these data suggest that DNAJB3 can potentially play a protective role against obesity." (PMID 23894433, 2013). "Our findings suggest that DNAJB3 may constitute a potential therapeutic agent in the treatment of obesity and diabetes, which warrants further basic and clinical research." (PMID 37895206, 2023). "It was demonstrated that the function of PPARs was modulated in obesity, suggesting that those might be the factors regulating the expression of DNAJB3 in obese patients." (PMID 26147428, 2015). "It was further demonstrated that the mRNA expression of DNAJB3 was restored by physical exercise, suggesting that DNAJB3 could potentially play a protective role against obesity." (PMID 26147428, 2015). "This suggests that DNAJB3 could be a potential target for therapeutic treatment of obesity-induced insulin resistance." (PMID 26400768, 2015). "Based on the inverse correlation between the levels of DNAJB3 and activated JNK and given the importance of stress kinases such as JNK, IKKβ in obesity and insulin resistance, we initially sought to determine if there is an interaction between DNAJB3 and these stress kinases." (PMID 23894433, 2013).
Obesity (continued). "Moreover, overexpression of DNAJB3 improves insulin signalling and glucose uptake in pre-adipocytes, suggesting DNAJB3 may have a protective role in obesity." (PMID 37594932, 2023). "In summary, our results shed the light on the possible role of DNAJB3 in improving insulin sensitivity and glucose uptake through JNK repression and suggest that DNAJB3 could be a potential target for therapeutic treatment of obesity-induced insulin resistance." (PMID 26400768, 2015). "All together, our data support the suggestion that DNAJB3 can potentially play a protective role against obesity, and thus targeting DNAJB3 may have a potential therapeutic benefit for the control and management of obesity and insulin resistance." (PMID 23894433, 2013). "Taken together, our data support the protective role that DNAJB3 may play against obesity." (PMID 23894433, 2013). "Our recent data demonstrated that DNAJB3, an HSP-40 protein family member, is downregulated in response to obesity in peripheral blood mononuclear cells (PBMCs) and subcutaneous adipose tissue and showed negative correlation with key pro-inflammatory markers such as IP-10 and RANTES24." (PMID 26400768, 2015). "In this study, given previously reported low levels of DNAJB3 in individuals with obesity and T2D, we investigated whether the lack of DNAJB3 would increase body weight, fat mass and glucose intolerance in mice fed high-fat diets." (PMID 37895206, 2023). "Unlike DNAJB3, this protein was found to be increased in obesity." (PMID 30131766, 2018). "In the context of obesity, no previous study reported the existence of mediators that could positively or negatively modulate the expression of DNAJB3." (PMID 23894433, 2013).
diabetes (3 papers, 2015 to 2023). "Metabolic stress involved in several dysregulation disorders such as type 2 diabetes mellitus (T2DM) results in down regulation of several heat shock proteins (HSPs) including DNAJB3." (PMID 37594932, 2023). "For instance, are DNAJB3 KO animals more prone to IR and diabetes?" (PMID 30886231, 2019). "The low expression of DNAJB3 in obese T2D subjects compared to non-diabetic subjects suggests a possible role of DNAJB3 reduction in the progression to diabetes." (PMID 26400768, 2015).
Insulin resistance (3 papers, 2013 to 2025). Increased resistance towards insulin, that is, diminished effectiveness of insulin in reducing blood glucose levels. "DNAJB3, for instance, has been reported to affect the stress-responsive kinases JNK1 and IKKβ to modulate insulin resistance in vitro." (PMID 41233317, 2025).
Type 2 Diabetes (3 papers, 2019 to 2023). "Understanding the intricate relationship between HSPs and their co-chaperone DNAJB3 is pivotal in unraveling the mechanisms underlying protein homeostasis and its implications in health and disease, including Type 2 Diabetes (T2D)." (PMID 37895206, 2023). "Altogether, our data provide for the first time a compelling evidence for a novel role of DNAJB3 in modulating metabolic stress; a prerequisite step that leads to IR and type 2 diabetes." (PMID 30886231, 2019). "Identifying small molecules that induce the expression DNAJB3 or recapitulate its function could be leveraged as a possible novel strategy for the control and management of metabolic defects leading to IR and type 2 diabetes." (PMID 30886231, 2019).
Glucose intolerance (1 paper, 2023). Glucose intolerance (GI) can be defined as dysglycemia that comprises both prediabetes and diabetes. "In conclusion, the absence of DNAJB3 potentially increases adiposity, glucose intolerance and inflammation in high-fat-diet-induced obese mice." (PMID 37895206, 2023). "We hypothesized that an animal model lacking DNAJB3 would have increased body weight, body fat, inflammation and glucose intolerance when fed obesogenic high-fat diets." (PMID 37895206, 2023).
metabolic disease (4 papers, 2015 to 2023). A congenital disorder (due to inherited enzyme abnormality) or acquired (due to failure of a metabolically important organ) disorder resulting from an abnormal metabolic process. "Recent findings from our group and others suggested a possible role of DNAJB3 in the pathogenesis of metabolic diseases associated with IR." (PMID 37594932, 2023). "There were no prior animal studies that had inactivated this gene, and the very limited published work on the role of DNAJB3 further complicates our understanding the functions of this gene in metabolic diseases." (PMID 37895206, 2023). "To further elucidate the effect of DNAJB3 on metabolic diseases and to develop a model for its mode of action, we conducted a series of in vitro cell line experiments using palmitate as a JNK activator." (PMID 26400768, 2015). "DNAJB3, previously known as MSJ-1 was initially identified in mice as a gene involved in spermatogenesis and while its co-chaperone activity is well established, its role in metabolic diseases is emerging." (PMID 37594932, 2023).
tumour (1 paper, 2018). "The Basal subtype showed the highest number of specific upregulated genes (DNAJC2, DNAJC6, HSPA5, HSPA14 and CRYAA), DNAJA3 and CCT2 were upregulated in Luminal B, and DNAJB3 was only upregulated in HER2 tumours." (PMID 29954368, 2018).
DNAJB3 also shares sentences with these, for which no sentence is quoted: hyperlipidemia (1 paper).